HRG (histidine rich glycoprotein)
Diseases named in the same sentence as HRG in open-access papers (continued):
Sharing a sentence is not in itself a finding about the gene and the disease.
tumor (76 papers, 2009 to 2025). "Parallel findings indicate that HRG supports specific populations of tumor-associated macrophages, playing a key role in NAFLD progression to HCC, indicating HRG as a promising prognostic marker and therapeutic target." (PMID 40625923, 2025). "The His/Pro-rich domain, also known as the histidine-rich region (HRR), is essential for HRG’s function and promotes tumor-associated macrophage (TAM) polarization, thereby inhibiting tumor growth." (PMID 39519855, 2024). "First, the action of HRG on the polarization of tumor-associated macrophages (TAMs) from an immunosuppressive M2- to a tumor-inhibiting M1-like phenotype contributes to promoting antitumor immune responses." (PMID 36430209, 2022). "The broadly expressed secreted protein stanniocalcin 2 (STC2), also implicated in tumor inflammation, is an HRG interaction partner." (PMID 36078092, 2022). "In several mouse tumor models HRG exerts gene regulatory effects in tumor‐associated macrophages resulting in a switch from an M2 to M1 polarity profile, correlating with enhanced antitumor immunity, decreased tumor growth, and reduced metastatic spread." (PMID 35847718, 2020). "It is well known that HRG promotes the transformation of M2 tumor-associated macrophages to the M1 phenotype, which inhibits tumor angiogenesis and cell proliferation 44,45." (PMID 32929358, 2020). "In the tumor environment, HRG promotes tumor-associated macrophage polarization into an antitumor (M1) phenotype." (PMID 30944671, 2019). "Histidine-rich glycoprotein (HRG) is implicated in tumor growth and metastasis by regulation of angiogenesis and inflammation." (PMID 25243896, 2014). "In cancer, HRG polarizes tumor-associated macrophages from a pro-angiogenic, immune-suppressive M2 phenotype towards an anti-tumor, immunity-promoting, M1 phenotype." (PMID 25243896, 2014). "Murine and clinical data indicate that HRG plays a significant role in MASLD/MASH progression to HCC by supporting a specific population of tumor-associated macrophages with pro-inflammatory response and pro-angiogenetic capabilities which critically support cancer cell survival." (PMID 38469298, 2024). "The comparison of G3 vs. G2 revealed additional features for 65 main proteins, including an increase in histidine-rich glycoprotein and highly significant abundance changes for 22 other proteins regulating the tumor microenvironment, linked with the presence of numerous activated T cells." (PMID 36430209, 2022). "The increased FXR expression is also inversely related to histidine-rich glycoprotein (HRG) protein that can be correlated to different stages of carcinogenesis such as nodal metastasis, invasion, large tumour size and is associated with poor survival and poor prognosis in patients." (PMID 35006466, 2021). "Similarly, the identified FXR/RXR pathway target HRG also promotes tumor-associated macrophage polarization towards the M1-like macrophage phenotype." (PMID 29100312, 2017). "To address whether HRG deficiency affects tumor development, we have crossed HRG knockout mice with the RIP1-Tag2 mouse, a well established orthotopic model of multistage carcinogenesis." (PMID 21264222, 2011). "Moreover, HRG by promoting tumor-associated macrophage polarization into an antitumor phenotype may result in tumor growth inhibition and it is a possible mechanism of cancer progression." (PMID 30944671, 2019). "It is also reported that HRG inhibits tumour growth and vascularization, remodels transition from epithelial to mesenchymal, and regulates the formation of protumorigenic microenvironment by skewing tumour-associated macrophages polarization from the M2-like towards M1-like phenotype." (PMID 31186631, 2019). "HRG has been described to inhibit tumor growth and metastasis by promoting M1 polarization of tumor‐associated macrophages and tumor vessel normalization." (PMID 40517318, 2025).
tumor (continued). "HRG, a protein mainly produced in the liver but can also be synthesized by monocytes and macrophages, has been shown to slow tumor growth in mouse models of various cancers, including GB." (PMID 40517318, 2025). "Given the essential role of angiogenesis in tumor progression, HRG’s ability to regulate this process presents a promising therapeutic strategy for cancer treatment." (PMID 40191430, 2025). "The HRG gene was correlated with anti-tumor immune cell infiltration, whereas TUBA1B gene was negatively correlated." (PMID 40171266, 2025). "In 2016, a study using a mouse tumor model demonstrated that histidine-rich glycoprotein (HRG), a plasma protein derived from the liver, facilitates the transition from alternatively activated (M2) to pro-inflammatory (M1) macrophages." (PMID 39273000, 2024). "Among these tumor suppressors is histidine-rich glycoprotein (HRG), which suppresses HCC by inhibiting proliferation and increasing apoptosis." (PMID 39796711, 2024). "We further explored the number of neutrophils after tumorigenesis in the lungs by flow cytometry and found that the number of neutrophils in HRG overexpressed tumours decreased and the number of neutrophils in HRG knockdown tumours and KO‐HRG mice increased." (PMID 37254661, 2023). "In the BF-TK/GCV/BF-TK group, the top five hub proteins were AMBP, HRG, APCS, HPX, and GIG25; some proteins (HRG, HPX, and GIG25) are positively associated with tumor metastasis." (PMID 37511481, 2023). "Studies have shown that overexpression of HRG in specific cancer cells leads to slower tumor growth and reduced metastasis in mice, even with persistent TAMs accumulation." (PMID 37626639, 2023). "It has been demonstrated that histidine-rich glycoprotein (HRG) can downregulate placental growth factor (PlGF) levels, leading to the restoration of tumor vessel functionality and TAM repolarization." (PMID 34603327, 2021). "HRG has been shown to inhibit tumor growth and metastasis and does so by downregulating PlGF to induce macrophage polarization and normalization of blood vessels." (PMID 32210020, 2020). "Downregulation of HRG in HCC tumor samples was confirmed by qRT-PCR (32 paired HCC samples) and western blotting (12 matched HCC tissues)." (PMID 32929358, 2020). "HRG expression by MZL tumor cells correlates with an altered transcription profile and improved overall survival." (PMID 35847718, 2020). "The idea of how to increase HRG level in HCC prompted us to investigate the nature of HRG downregulation in tumor samples and methods to restore its expression." (PMID 32929358, 2020). "In tumor models, HRG upregulation downregulated M2 markers such as IL-10, CCL22, and PlGF, while simultaneously increasing M1 markers such as IL-6 and CXCL9." (PMID 33218096, 2020). "Researches demonstrated that histidine-rich glycoprotein (HRG) involves both inflammatory promoting effect in chronic liver disease and tumor suppression during the development of HCC 23-25." (PMID 32929358, 2020). "In 2011, Rolny and colleagues reported that the expression level of HRG in tumor tissues was weaker than that found in healthy counterparts." (PMID 30821275, 2019). "Very recently, HRG was proved to suppress tumor growth and metastasis by inducing macrophage polarization and vessel normalization, as well as regulating platelet activity." (PMID 30821275, 2019). "HRG reversed polarization of TAMs into tumor-inhibiting M1 macrophages via downregulation of the placental growth factor, a member of the VEGF family." (PMID 28660349, 2018). "It was proved that HRG inhibits tumor growth and metastasis, promotes antitumor immune responses, and induces vessel normalization." (PMID 28660349, 2018). "HRG, a host-produced antiangiogenic and immunomodulatory factor, has been reported to promote anti-tumor immune responses and vessel normalization by skewing TAM polarization away from the M2- to a tumor-inhibiting M1-phenotype." (PMID 27191744, 2016).
tumor (continued). "Using a 3D CRC cell culture model, we here show for the first time that K-RasG12V induced hyperproliferation and loss of polarized morphogenesis, both of which are hallmarks of tumor progression, engage a HRG/ErbB3 dependent signaling loop." (PMID 27447549, 2016). "The study was supported by Tugues, who found that conversion of macrophages toward M2-like by depleting histidine-rich glycoprotein (HRG) leading to excessive pro-angiogenic gene expression and increased tumor volume." (PMID 26411672, 2015). "Compared to the control group, HRG overexpression resulted in significant inhibition of tumor growth." (PMID 26336134, 2015). "Administration of the heparin-binding plasma protein HRG to tumor-bearing mice has a decisive impact on the tumor microenvironment, leading to an improved vessel function and the mobilization of an anti-tumor immune response." (PMID 25243896, 2014). "HRG has been studied to identify mechanisms by which it mediates anti-tumor effects; and the results revealed that TAMs activated by HRG down regulated expression of pro-angiogenic cytokines and upregulated that of angiostatic cytokines." (PMID 26932379, 2014). "In contrast, there was a dramatic decrease in HRG immunostaining intensity in the stroma of tumor tissue samples from CRC as well as lymphatic and distant metastases." (PMID 25243896, 2014). "The heparin-binding protein histidine-rich glycoprotein (HRG) has received increasing attention due to its role in diverse processes such as bacterial infection and tumor development." (PMID 25243896, 2014). "In another model, overexpression of the histidine-rich glycoprotein (HRG) induces tumor vessels normalization through a down regulation of PlGF, and at the same time, leads to an increase of CD8+ lymphocyte infiltration within the tumor." (PMID 24765614, 2014). "In the present study, HRG−/− mice were found to have a larger tumor volume compared to their HRG+/+ littermates." (PMID 21264222, 2011). "To investigate how lack of HRG affects pathological angiogenesis in established tumors we performed stereological quantification of tumor vascularization in 12 weeks old RT2/HRG+/+ and RT2/HRG−/− mice." (PMID 21264222, 2011). "At 12 weeks of age, HRG−/− mice have an approximately two times larger tumor volume than HRG+/+ mice." (PMID 21264222, 2011). "The heparin-binding plasma protein histidine-rich glycoprotein (HRG; alternatively, HRGP/HPRG) can suppress tumor angiogenesis and growth in vitro and in vivo." (PMID 21264222, 2011). "In summary, this study shows for the first time that tumor growth is enhanced in mice that lack HRG." (PMID 21264222, 2011). "To determine HRG expression in tumors we initially tried immunostainings for HRG protein on tumor sections." (PMID 20046875, 2009). "Instead, since RCAS is a retrovirus we decided to analyze RCAS mediated insertion of PDGF-B and HRG cDNA in genomic DNA isolated from tumor tissue." (PMID 20046875, 2009). "In addition, HRG inhibits tumor angiogenesis by modulating macrophage polarization and affecting key signaling pathways that control the migration and proliferation of endothelial cells." (PMID 40191430, 2025). "Interestingly, the analysis of HRG transcripts and immunohistochemistry showed that HRG expression was significantly lower in tumor tissue compared with normal liver parenchyma." (PMID 38469298, 2024). "HRG dysfunction may promote tumor tissue growth by disrupting the balance between pro- and anti-angiogenic factors." (PMID 39896931, 2024). "We observed that HRG is a key regulator of lung metastasis in HCC in vivo experiments but not in vitro experiments and that HRG is associated with diverse immune cells in the tumour microenvironment." (PMID 37254661, 2023). "And we found that mainly hepatocytes and tumour cells expressed HRG." (PMID 37254661, 2023). "Additionally, HRG is involved in the molecular processes related to cell adhesion, angiogenesis, coagulation, and tumor progression." (PMID 37627907, 2023).
tumor (continued). "We have previously shown that HRG, either administered as a recombinant protein, overexpressed by tumor cells, or delivered through adenovirus-mediated gene therapy, polarizes monocytes/macrophages to an anti-tumor immune profile, allowing for the recruitment of cytotoxic T cells to the tumor." (PMID 36078092, 2022). "Several proteins that are involved in tumor vascularization were detected: histidine-rich glycoprotein (HRG), α-2-HS-glycoprotein, leucine-rich α-2-glycoprotein (LRG), secreted GRP78, macrophage migration inhibitory factor (MIF), VEGFA, and hepatoma-derived growth factor." (PMID 35659255, 2022). "Furthermore, another two hypomethylated genes, MUC15 and HRG, exhibited downregulated mRNA levels in the tumor group." (PMID 35126463, 2021). "Whether HRG-mediated mechanisms in the tumor microenvironment could play a positive role in the immune response against cancer cells, how they influence a pregnancy remains to be elucidated." (PMID 33218096, 2020). "Thus, HRG expression by MZL tumor cells is accompanied by changes in gene expression, including DEFA1, characteristic of an antitumoral response." (PMID 35847718, 2020). "Restoring HRG expression in HCC tissues might be a promising pharmacological approach to blocking tumor progression by shifting cellular fate from cell survival to apoptosis." (PMID 32929358, 2020). "In the SHERBOC trial, tumor tissue had to be tested for HRG expression." (PMID 33176725, 2020). "Accordingly, our investigation revealed that restoring HRG expression in HCC cells might be a new approach to inhibiting tumor progression." (PMID 32929358, 2020). "HRG‐positive tumor cells, identified based on morphology, were present in patient subsets." (PMID 35847718, 2020). "Indeed, the growth of both HRG+ and control tumor cells was reduced to the same extent when transplanted in plgf-/- mice." (PMID 31216652, 2019). "In addition, HRG is deposited in the tumor stroma, although its levels are decreased in human cancer, both because tumor cells usually express low levels of HRG and because HRG is partially degraded to inactive fragments by tumors." (PMID 31216652, 2019). "At present, HRG is known as an important protein in the suppression of tumor progression." (PMID 30821275, 2019). "Therefore, in the case of the tumourigenic environment and the presence of this anti-angiogenic peptide (HRGP330) observed in the plasma of healthy and cancer patients, it can be deduced that HRG is involved in suppressing tumour progression." (PMID 28257077, 2017). "These interactions are further supported by recent studies highlighting the significance of peptide mimetics derived from the TSR domain of proteins such as TSP-1 in reducing angiogenesis of tumours by inhibition of CLESH-1-containing proteins such as HRG or CD36." (PMID 28257077, 2017). "Furthermore, as these factors can also vary depending on the nature of the injurious site, such as an acute or chronic wound, or at a site of tumour growth, this suggests that the regulation of HRG function will be specific within different sites." (PMID 28257077, 2017). "Additionally, signal molecules produced by tumor cells, such as lactate, HRG/PIGF, chemokine ligand 2 (CCL2), soluble colony-stimulating factor 1 (sCSF1), and POSTN, play critical roles in macrophage polarization." (PMID 27683110, 2016). "To determine whether the increased turnover of HRG observed in tumor-bearing mice bore any significance for steady-state levels of HRG, we employed ELISAs specific to either the mouse or human HRG protein." (PMID 25243896, 2014). "When administration of the anti-GP1bα antibody was initiated at a later stage (age nine weeks), after the onset of the angiogenic switch, platelet depletion did not suppress tumor growth in HRG-deficient mice." (PMID 21264222, 2011). "This suggests that HRG may have great potential in inhibiting tumour metastasis and recurrence." (PMID 37254661, 2023).
tumor (continued). "Therefore, HRG can function as a tumor suppressor to inhibit EMT by regulating platelet activity." (PMID 35659308, 2022). "The plasma-protein histidine-rich glycoprotein (HRG), a cation- and heparin- binding plasma glycoprotein, controls the phenotypic switching of macrophages through enhancing cytokine production and phagocytotic activity in tumours, resulting in the vessel normalization and antitumor immune responses." (PMID 35501821, 2022). "Therefore, it may be possible that HRG exerts antitumor activity by enhancing direct antitumor killing and tumor immunosurveillance." (PMID 31143450, 2019). "Interestingly, when administration of the anti-GP1bα antibody was initiated after the onset of the angiogenic switch, platelet depletion did not suppress tumor growth in HRG-deficient mice." (PMID 21264222, 2011). "However, if GP1bα treatment was initiated at a later stage, after the onset of the angiogenic switch, no suppression of tumor growth was detected in HRG-deficient mice." (PMID 21264222, 2011). "In the present study we describe three main findings; 1) tumor growth is significantly increased in HRG-deficient mice, 2) platelet activation is enhanced in mice lacking HRG and 3) the increased platelet activation mediates the accelerated angiogenic switch seen in HRG-deficient mice." (PMID 21264222, 2011). "Based on the results of our study, the HRG gene and the TUBA1B gene can predict the prognosis of HCC and accurately respond to the tumor immune microenvironment." (PMID 40171266, 2025). "In our study, we further utilized IHC staining to assess the protein expression of HRG and TUBA1B in tumor and normal tissues." (PMID 40171266, 2025). "To validate the prognostic value of the prognostic genes, we used the IHC stain to detect the protein expression of HRG and TUBA1B in tumor tissues and normal tissues." (PMID 40171266, 2025). "On the same vein, Deuschle and coworkers have reported that HRG transcripts are significantly lower in human HCC than normal or non-tumoral liver, with a progressive decrease according to the tumor stage." (PMID 38469298, 2024). "Histidine-rich glycoprotein (HRG), is a host-produced immunomodulatory and antiangiogenic factor that regulates tumor vessel formation and inflammation." (PMID 32656079, 2020). "It is likely that HRG/PIGF/M1-type TAMs enhance the antitumor immune response and facilitate vessel normalization, effects known to hinder tumor growth and metastasis and to facilitate chemotherapy." (PMID 32656079, 2020). "Histidine-rich glycoprotein (HRG), a multidomain plasma protein synthesized by hepatocytes, has been reported to skew TAM polarization away from the M2- to a tumor-inhibiting M1-phenotype in orthotopic Panc02 tumor models." (PMID 27191744, 2016). "The results showed that HRG overexpression in Huh7 and MHCC-97H cells induced marked reductions in cell proliferation, colony formation, and tumor growth, and promoted cell apoptosis." (PMID 26336134, 2015). "RIP1-Tag2 HRG−/− mice display significantly larger tumor volume compared to their RIP1-Tag2 HRG+/+ littermates, supporting a role for HRG as an endogenous regulator of tumor growth." (PMID 21264222, 2011). "To investigate the role of HRG in mice with intact immune activeness, WT and KO‐HRG mice were tail vein injected with mouse HCC cell line Hepa 1−6, and we found that KO‐HRG mice showed significantly higher intrapulmonary metastatic tumour loads than WT mice." (PMID 37254661, 2023). "In the MZL tumor samples in contrast, HRG expression did not correlate with an increased presence of CD4+ or CD8+ T cells, or CD68+ macrophages." (PMID 35847718, 2020). "Rolny and colleagues observed that switching macrophage polarization from M2 to M1 phenotype by histidine-rich glycoprotein (HRG) promotes vessel normalization and anti-tumor immune response, finally leading to enhanced chemotherapy and tumor growth regression." (PMID 28848446, 2017).